IFNG (interferon gamma)
Diseases named in the same sentence as IFNG in open-access papers (continued):
Sharing a sentence is not in itself a finding about the gene and the disease.
Hepatitis (140 papers, 2008 to 2026). Inflammation of the liver. "Hepatitis caused by this strain seems to be T-cell-mediated given that higher frequencies of IFNγ-producing CD8 T cells were associated with more severe disease and depletion of either CD8 or CD4 T cells reduced the severity of MCMV-induced hepatitis." (PMID 39134803, 2024). "Both T cells and macrophages play key roles in ConA-mediated hepatitis by producing TNFα and IFNγ, both of which cause liver injury." (PMID 30462657, 2018). "Meta-analysis of interferon gamma +874T/A polymorphisms and hepatitis virus-related diseases." (PMID 25939029, 2015). "ConA-induced hepatitis is mediated, at least in part, by the prototypic Th1 cytokines IFNγ and TNFα." (PMID 34305911, 2021). "In a model of hepatitis, artesunate treatment inhibited production of inflammatory cytokines such as interferon gamma and tumor necrosis factor alpha while driving production of the anti-inflammatory IL-1017." (PMID 31420579, 2019). "Our results demonstrate that peripheral dopamine controlled by gut microbes inhibits IL4 and IFNγ production in iNKT cells and suppresses iNKT cell-mediated hepatitis." (PMID 30386344, 2018). "In ConA-induced hepatitis, TNFα and IFNγ are rapidly produced in response to ConA and induce the expression of pro-inflammatory proteins in both parenchymal and non-parenchymal liver cells." (PMID 30323351, 2018). "In summary, we demonstrate that peripheral dopamine controlled by gut microbes inhibits IL4 and IFNγ production in iNKT cells and suppresses iNKT cell-mediated hepatitis." (PMID 30386344, 2018). "Following ConA activation, lymphocytes produce IFNγ, which is directly involved in the pathogenesis of ConA-induced hepatitis." (PMID 26287688, 2015). "E.g., rhesus macaques reacted to a gene gun vaccine encoding HIVgp160 with a balanced Th1/2 response and, in human volunteers, a hepatitis B gene gun vaccine induced cellular responses dominated by IFNγ-secreting Th1 cells." (PMID 25025197, 2014). "Furthermore, depletion of NK cells and neutralization of IFNγ resulted in exacerbated hepatitis outcomes." (PMID 39134803, 2024). "IL-12, a known potent inducer of IFNγ production in NK cells, improves NK cell antiviral responses, and administering low doses of IL-12 decreases the viral titer in the liver and improves hepatitis incidence." (PMID 39134803, 2024). "Evidence from immunohistologic studies showed that there was CD8+ T cells infiltration and increased production of interferon gamma (IFN-γ) during the acute flare of chronic hepatitis B, as well as increased HBcAg/HBeAg-specific T cells before and during the hepatitis flares." (PMID 35163330, 2022). "Elevated IFNγ levels in serum have been correlated with systemic symptoms of reactogenicity 7 days post-vaccination with a modified live smallpox vaccine and after booster doses of a liposome adjuvanted hepatitis vaccine." (PMID 34616410, 2021). "Congruently, ablation of interferon gamma (IFN-γ, encoded by IFNG), a prototypical T cell cytokine, or its cognate receptor (IFNGR1/R2), or its downstream mediator IRF-1 attenuates ConA-induced hepatitis in mice." (PMID 33553140, 2020). "This may mimic events in vivo in which an inflammatory hepatic cytokine microenvironment, found in hepatitis or cancer, dominated by IL‐1, IL‐2, IL‐6, IL‐12, IL‐15, IL‐18, IFNα, IFNγ, and TNFα/β 38, 39, may lead to the expansion of CD49a+ NK cells." (PMID 28952190, 2018). "In addition, more CD4+ T cells than macrophages expressed these cytokines, suggesting that CD4+ T cells are the main source of TNFα and IFNγ during ConA hepatitis." (PMID 30462657, 2018). "However, the IFNγ was strongly induced in WT mice with less profound expression in IL-33 KO mice demonstrating that endogenous IL-33 regulated IFNγ expression during L2-MHV3 hepatitis." (PMID 28607531, 2017).
Hepatitis (continued). "Indeed, pretreatment of MSCs with IFNγ has already been shown to significantly increase therapeutic effects in mice suffering from graft-versus-host disease or hepatitis." (PMID 27729913, 2016). "Thus, 74 HC with known hepatitis B vaccination status were also analyzed regarding their HBsAg-dependent IFNγ and IL2 release." (PMID 25968473, 2015). "Because of the key role of T cells, T cell-derived IFNγ, and B cells in the pathogenesis, this may represent a useful in vivo model system to examine T cell induced liver inflammation." (PMID 25313460, 2014). "Importantly, alum delivered vaccines have been shown to prime IFNγ producing CD8 T cells in humans immunized with hepatitis B vaccine." (PMID 23613928, 2013). "In addition to IFNγ and IL-4, osteopontin produced by activated NKT also contributes to ConA-induced hepatitis, indicated by the resistance to ConA-induced hepatitis by osteopontin-deficient mice." (PMID 22347449, 2012). "The major cytokines involved in hepatitis development are tumor necrosis alpha (TNF-α), interferon gamma (IFN-γ), interleukin-2 (IL-2), and IL-6, of which TNF-α and IFN-γ are the dominant cytokines in irreversible biological damage." (PMID 27035150, 2016). "Inflammatory cytokines such as IFNγ, IL-4 and TNFα that are produced by activated NKT cells are essential mediators for induction of hepatitis." (PMID 22347449, 2012). "Proteins that uniquely distinguish HCC patients with low AFP from patients with hepatitis include IL1RN, IFNG, CDKN1A, RETN, CXCL14, and FGF2." (PMID 19578489, 2008). "Additionally, compound 34 strongly reduced serum concentrations of TNFα, IFNγ, and IL-4, and diminished serum ALT and AST activities in ConA-induced hepatitis in mice." (PMID 35631676, 2022). "Recent studies reported that Vδ2+ γδT cells from patients with chronic HBV-infection with hepatitis flares responded less to IFNγ/TNF than those without hepatitis flares." (PMID 34360777, 2021). "Further, IFNγ/TNF responses were weaker in Vδ2+ γδT cells from chronic HBV infected patients with hepatitis flare when compared to those without hepatitis flare." (PMID 31507621, 2019). "Accordingly, IFNγ/TNF responses in Vδ2+γδT-cells were weaker in patients with CHB with hepatitis flare compared to those without hepatitis flares, and this functional deficit persisted beyond clinical resolution of CHB flare." (PMID 30998783, 2019). "Importantly, we also identified 8 proteins that significantly differentiate HCC patients with ‘normal’ levels of AFP (< 20 ng/ml) from hepatitis patients (p < 0.05) (IL1RN, IFNG, CDKN1A, RETN, CXCL14, CTNNB, FGF2, and SELL)." (PMID 19578489, 2008). "Given the inverse associations between serum ALT and early IFNγ/TNF responses in γδT-cells to PMA/Ionomycin stimulation in CHB, CHB subjects with and without a recent hepatitis flare (ALT/ULN ≥10 within a month of immune analyses) were further compared for IFNγ/TNF responses in γδT-cells." (PMID 30998783, 2019). "Furthermore, in CHB, IFNγ/TNF responses to brief PMA/Ionomycin stimulation in Vδ2+ γδT-cells correlated inversely with serum alanine aminotransferase (ALT), with persistent deficit in patients with hepatitis ALT flares compared to those without flares." (PMID 30998783, 2019).
Stroke (140 papers, 2009 to 2025). Sudden impairment of blood flow to a part of the brain due to occlusion or rupture of an artery to the brain. "In addition, IFNγ has been associated with stroke-induced neurodegeneration since it is pro-inflammatory." (PMID 38166692, 2024). "Meanwhile, the IFNγ may aggravate the astherosclerosis and associated with the stroke even in the lower level of the ACOS cohort compared with the control group." (PMID 29552322, 2018). "Proinflammatory cytokines such as IFNγ, are a likely candidate given that IFNγ receptors are expressed on microglia and its signaling is induced by brain injury such as stroke or hemorrhage, where it regulates many facets of macrophage behavior." (PMID 37428916, 2023). "IL-10 and interferon-gamma (IFN-γ) were associated with the development of arrhythmia after CABG surgery, and in a cohort study, the second was considered a marker for stroke prediction and all-cause mortality in patients with new-onset AF." (PMID 36834735, 2023). "Monocytes isolated from stroke patients or from rats following experimental stroke display reduced ability to produce the pro-inflammatory cytokines TNFα and IFNγ after stimulation with the bacterial endotoxin LPS." (PMID 38566903, 2022). "Increased circulating IL-10 and decreased IFNγ concentrations correlate with the development of infection in patients after stroke." (PMID 38566903, 2022). "This shift is characterized by reduced concentrations of circulating IFNγ and elevated IL-10 following stroke." (PMID 38566903, 2022). "Immune-modulatory approaches involving T-cell transfer, natural killer T-cell (NKT) activators and interferon-gamma (IFN-γ) have shown benefit in reducing post-stroke immunosuppression." (PMID 35250546, 2022). "Similar functional deficits are observed in the acute phase following stroke, as NK cells isolated from stroke patients produce less IFNγ and perforin." (PMID 38566903, 2022). "CNS-specific Th1 cells secrete interferon gamma (IFNγ) after stroke and activate cytotoxic CD8+ T cells that exacerbate CNS damage." (PMID 34299322, 2021). "A splenectomy performed 2 weeks prior to stroke onset or the administration of antibodies to neutralize IFNγ significantly reduced neurodegeneration at 96 h post-MCAO." (PMID 30322390, 2018). "Although CD3 is expressed by all T cells, this reduction coupled with the downregulation in IFNγ production suggest that LIF prevents the maturation of CD8+ cytotoxic T cells, which are the major producer of IFNγ after stroke." (PMID 30322390, 2018). "Previous studies in animal models and in stroke patients have shown that continued production of cytokines such as IFNγ, TNFα, IL11, IL-1β, IL-1ra and IL-6 induces and maintains the M1 polarization state." (PMID 30584250, 2018). "Not only has the spleen been shown to decrease in size following stroke there is also an increase in IFNγ in subjects with splenic contraction." (PMID 29970193, 2018). "Our lab has demonstrated an essential role for T and NK cell-derived IFNγ in the initiation of the post-stroke splenic response." (PMID 30322390, 2018). "Choroid plexus tissues were collected and analyzed for Vcam1, Madcam1, Cx3cl1, Ccl2, Nt5e, and Ifnγ expression at different timepoints after stroke using qPCR." (PMID 28754163, 2017). "In a mid cerebral artery model of stroke, IL-10 administration was found to suppress overexpression of proinflammatory mediators IFNγ and TNFα and reduce lesion volume." (PMID 27022620, 2016). "Functional elimination by splenectomy or administration of IFNγ neutralizing antibodies reduced brain injury after stroke." (PMID 26700169, 2015). "More specifically IL-1, IL-6, IL-10, IL-17, IL-23, TNFα, transforming growth factor β (TGFβ) and IFNγ are seen to increase after stroke, IL-17, IL-23 and IFNγ being associated with exacerbation of stroke in mice, whereas IL-10 and TGFβ are protective." (PMID 25705177, 2015).
Stroke (continued). "Blockade of interferon gamma signaling has been reported to be neuroprotective in experimental stroke although other groups have reported alternative results in their model systems." (PMID 25368553, 2014). "Stroke also results in a shift from pro-inflammatory Th1 to anti-inflammatory Th2 response in animal stroke models and a significantly lower ratio of IFNγ/IL-4-producing T cells in human patients." (PMID 23555048, 2013). "These cells are also capable of antagonizing the production of proinflammatory cytokines (TNF-α and IFNγ), that induce secondary brain damage during stroke." (PMID 21192826, 2010). "In addition, Rep-Mo/MΦ demonstrated the enrichment of “response to interferon-gamma” genes (Ifitm1 and Ifitm6), which has been shown to promote microglial migration and exacerbate brain injury of stroke." (PMID 40777042, 2025). "IFNγ plays a pivotal role in shaping the inflammatory microenvironment in AD, PD, MS and stroke." (PMID 40083634, 2025). "Microglial polarization is triggered by DAMPs and IFNγ stimulation, which activate the NF-kB and STAT1 pathways, similar to macrophages, resulting in the release of cytokines including IL-1β and TNF-α that cause neuronal death following stroke." (PMID 39062789, 2024). "Reduced production of IFNγ by lymphocytes persists for at least 3 months after stroke." (PMID 38566903, 2022). "In C57BL/6 mice at 7 weeks post-stroke there were increased levels of G-CSF, GM-CSF, IFNγ, IL-1α, IL-5, IL-6, IL-12 (p40), IL-12 (p70), IP-10, KC, MCP-1, MIP-1α, MIP-1β, MIP-2A, RANTES, and TNFα within the infarct compared to the equivalent area of cortex from sham mice." (PMID 27600707, 2016). "Spleen derived IFNγ directly contributes to neurodegeneration related to stroke." (PMID 25309326, 2014). "Through this study and previously published manuscripts, this lab has demonstrated that LIF treatment after stroke promotes neuroprotection and recovery through two distinct mechanisms: Akt-dependent upregulation of antioxidant enzymes and modulation of the IL-12 p40/IFNγ/IP-10 signaling pathway." (PMID 30322390, 2018). "Moreover, addition of interferon gamma reverses the neuroprotection provided by splenectomy, demonstrating that this cytokine plays a major role in the spleen eliciting response resulting in further neural death after stroke." (PMID 25368553, 2014). "Following stroke, substantial skewing of the cytokine response is observed, with a shift from a TH1 (IFNγ) to TH2 (IL-4, IL-10) phenotype." (PMID 38566903, 2022). "Administration of antibodies to block the IFNγ/CXCL10 signaling yields a significant decrease in the infarct volume and prevents the reduction in spleen size at 72 h after stroke." (PMID 33376583, 2020). "By counteracting the IFNγ-mediated increase in splenic IP-10, LIF treatment would decrease the number of pro-inflammatory immune cells migrating to the brain after stroke." (PMID 30322390, 2018). "We report that TNF‐α, IFNγ, MIP‐1α, and MCP‐1 are reduced 48 hr after stroke, supporting our previous finding that BML‐111 reduces neutrophil infiltration at 48 hr post‐stroke." (PMID 28523230, 2017). "At 48 hr post‐stroke, BML‐111 reduced levels of pro‐inflammatory cytokines TNF‐α and IFNγ compared to levels in the vehicle‐treated rats (p = .0638, p < .01, respectively)." (PMID 28523230, 2017). "In BALB/c mice at 7 weeks post-stroke, levels of G-CSF, IL-2, IL-6, IL-17, IP-10, MCP-1, and RANTES were increased, and levels of GM-CSF, IFNγ, IL-10 were decreased compared to sham mice." (PMID 27600707, 2016). "CD4+ regulatory T cells are upregulated following stroke and CD8+ regulatory T cells are known to suppress CD4+ and CD8+ T cell proliferation and IFNγ production by secreting IL-10." (PMID 25309326, 2014). "Interferon-gamma (IFNγ), a proinflammatory cytokine produced by CD4+ T cells, CD8+ T cells, and NK cells, is largely responsible for initiating the peripheral immune response after stroke." (PMID 33376583, 2020).
Stroke (continued). "Also, LIF treatment promotes anti-inflammatory signaling by decreasing splenic levels of IFNγ and preventing the upregulation of CXCL10 that occurs after stroke." (PMID 33376583, 2020). "Most recently, Wong and colleagues reported that stroke led to the activation of the SNS, which innervates iNKT cells in the liver, causing iNKT cells to secrete immunosuppressive cytokine IL-10, rather than pro-inflammatory IFNγ, thus resulting in SIID." (PMID 23555048, 2013). "Consequently, within the first 24 h after stroke onset, microglia undergo a phenotypic shift from a resting state (M0) to a pro-inflammatory M1 phenotype, producing and releasing pro-inflammatory cytokines such as the TNF-α, interferon-gamma (IFN-γ) IL-1β, IL-6, and IL-12." (PMID 38540114, 2024).
Salmonella Infections (136 papers, 2008 to 2025). Infections with bacteria of the genus SALMONELLA. "IFNγ regulates mucin production during Salmonella infection and deficiency of the mucin MUC2 increases susceptibility to infection in a mouse model." (PMID 37483638, 2023). "Defective IFNγ or IL12 production or receptor signaling pathways led to heightened susceptibility to Salmonella infection." (PMID 33804435, 2021). "In order to unravel the causal relationship between IL-18, IFNγ and infection outcome, we reconstituted IL-18 and IFNγ in stopΔIEC mice and compared their susceptibility at early time points (18 hpi) of Salmonella infection." (PMID 32330185, 2020). "Limited information is available regarding the mechanism underlying LGG-mediated regulation of the IFNγ-producing CD3-CD19- cell subset via T-bet to control Salmonella infections." (PMID 31134022, 2019). "IFN-γ is produced in response to Salmonella infection and is encoded by IFNG which was strongly induced in both WT and MUT loops in this study consistent with previously published results." (PMID 22096503, 2011). "Patients with defects in the IL-12/IFNγ activation pathways are at increased risk of severe mycobacterial and Salmonella infections, and recombinant IFNγ is an established therapy in patients with chronic granulomatous disease." (PMID 20195505, 2010). "Similarly to Salmonella infection, LPS transfection only caused cell death in IFNγ-primed HeLa and was completely abrogated by deletion of CASP4 or GSDMD." (PMID 32581219, 2020). "At the late stage of Salmonella infection, AvrA is associated with interferon-gamma responses." (PMID 21182782, 2010). "However, Salmonella infections cause severe enterocolitis that is at least partly driven by IFNγ." (PMID 31134022, 2019). "In agreement with the strong decrease of IFNγ we found that the increase of IL-10 on CD4+ T cells in Salmonella infection is time dependent with the highest levels in iron fed Tim3−/− mice." (PMID 40939292, 2025). "We demonstrate that during iron loading conditions TIM-3 controls IL-10 formation and improves Th1 mediated IFNγ formation leading to better control of Salmonella infection." (PMID 40939292, 2025). "A recent study showed that Salmonella infection induced migration of intestinal RORγt+ T-bet+ ILCs to mesenteric lymph nodes which contributed to the protective IFNγ response." (PMID 37483638, 2023). "During the initial phase of systemic Salmonella infection, a pro-inflammatory immune response is initiated, mainly driven by pro-inflammatory (M1) macrophages and the T cell and NK cell derived cytokine IFNγ." (PMID 37190073, 2023). "Since IFNγ increases SLAMF8 expression, and activation of pMø through IFNγ is crucial for Salmonella infection, we decided to analyze the impact of SLAMF8 in Salmonella-infected Mø." (PMID 35837407, 2022). "Further, studies with depletion of ILCs indicate a reduced IFNγ and mucus secretion after Salmonella infection." (PMID 36430676, 2022). "Inflammatory cytokines increase during the early phase of Salmonella infection, and IFNγ is upregulated during a later phase." (PMID 34843525, 2021). "Additional mechanistic studies are needed to dissect the role of ILC-produced IFNγ in maintaining the integrity of epithelial barrier during Salmonella infection." (PMID 34938670, 2021). "Experiments with depletion of ILCs revealed reduced IFNγ and mucus secretion after Salmonella infection." (PMID 34938670, 2021). "In the three recipients surviving Salmonella infection, their serum IFNγ increased from 14.2, 90.2, and 108 pg/mL before challenge to 1356, 568, and 190 pg/mL after challenge, respectively, whereas serum IL4 was not detectable before or after challenge." (PMID 33804435, 2021). "It was also found that LTβR-/- mice display an impaired production of IFNγ in response to chronic Salmonella infection." (PMID 34938670, 2021).